BMP2 (bone morphogenetic protein 2)
Diseases named in the same sentence as BMP2 in open-access papers (continued):
Sharing a sentence is not in itself a finding about the gene and the disease.
diabetes (continued). "HRECs treated with BMP2 showed upregulated mRNA levels of BMP2 and TGFβ, which may suggest the presence of a link between elevated circulating BMP2 levels in diabetes and retinal BMP2 upregulation." (PMID 33919531, 2021). "Importantly, the highest in loco expression of both NF-κB and BMP-2 was seen in individuals with poorly controlled diabetes." (PMID 34494136, 2021). "The increased expression of BMP2 in HRECs subjected to exogenous rhBMP2 may establish a link between increased blood levels of BMP2 and its upregulation in retina during diabetes." (PMID 33584642, 2020). "Bone morphogenetic proteins have been implicated in glucose metabolism and it has been proposed that BMP2 rs235756 is associated with SF levels in p.C282Y homozygotes, although we found no documentation of the relationship of BMP2 rs235756 to diabetes risk." (PMID 28331855, 2017). "In this study, we found a similar conclusion that higher CAC scores in outpatients with suspected CAD are related to diabetes, and that oxidative stress and endothelial dysfunction induced by BMP-2 might be the important intermediate links." (PMID 27733980, 2016). "Second, emerging biologics (e.g., recombinant human bone morphogenetic protein-2, teriparatide) may counteract the detrimental osseous effects of diabetes; stratified analyses could determine whether their benefit is more pronounced in patients exceeding the pre-operative HbA1c threshold." (PMID 40648963, 2025). "Thus, diabetes augments ER stress with concomitant increase in the expression of Tbx20 and Bmp2." (PMID 36805334, 2023). "Therefore, the BMP family may be an exciting prospect for future treatments of diabetes as BMP2, BMP6, BMP7, and BMP 9 have function of improving glucose metabolism." (PMID 34258293, 2021). "This raises a question regarding this difference between type 1 and type 2 diabetes and whether relative long exposure to hyperglycemia in STZ (6 months) and Akita (12 months) versus 10–12 weeks in db/db played a role in this differential effect of diabetes on plasma levels of BMP2." (PMID 33584642, 2020). "Beyond IL-4 and IL-10, other members of the TGF superfamily, such as TGF-β3, BMP-2, and BMP-4, are involved in regulating macrophages for bone regeneration in diabetes as well, making them potential targets in future research on biomaterial-based therapy." (PMID 39258053, 2024). "On the other hand, mRNA expressions of DKK1, BMP-2, OSN, RUNX2, and LRP5, which decrease with diabetes in bone tissue, increase significantly with MF administration." (PMID 39202505, 2024). "In vitro studies have revealed that scopoletin (1–20 μM) improves osteoclast formation in diabetes through RANKL and enhances osteoclast formation in diabetes by inducing BMP-2 and Runx2." (PMID 38464713, 2024). "Metformin can also improve the progression of diabetes through the AMPK regulation and affect the expression of BMP-2 levels, and it can also improve bone metabolism." (PMID 35027504, 2022). "The expression of protein Rankl was significantly increased and the expressions of proteins BMP2, OPG, OPN, and Runx2 were significantly decreased in diabetic mice (Diabetes-control, D-control) compared with normal mice (Wild-control, W-control) (p < 0.05)." (PMID 36632609, 2021). "The increase in circulating BMP2 in STZ and Akita mice was reported after 6 and 12 months from the onset of diabetes, respectively." (PMID 33584642, 2020). "Moreover, increases in the circulating BMP2 was reported here at early and late stage of diabetes, 6 week–12 months from onset of the experimental diabetes leading us to hypothesize that the circulating level of BMP2 could be a biomarker in the diabetic patients." (PMID 33584642, 2020). "The study reveals that glutaminolysis in macrophages is inhibited under type 2 diabetes mellitus (T2DM) conditions, which impedes fracture healing by reducing bone morphogenetic protein 2 (BMP2) production through increased cytosine methylation on the promoter." (PMID 39996573, 2025).
diabetes (continued). "Recently, it was reported that BMP-2 expression was decreased in patients with chronic HF with diabetes, and BMP-2 levels were negatively correlated with the levels of ANP and BNP in patients with CHF and diabetes." (PMID 36909186, 2023). "Compared with non-diabetic subjects, patients with diabetes show increased vascular calcification and upregulation of bone-related proteins, such as osteopontin, type I collagen, bone morphogenetic protein-2 (BMP-2) and TNAP in the medial layer of the vessels." (PMID 33816463, 2021). "AdipoRon suppressed the expression of protein Rankl and promoted the expressions of BMP2, OPG, OPN, and Runx2 in diabetic mice significantly (p < 0.05), which suggested that AdipoRon suppressed the diabetes-induced osteoclast formation and promoted the osteoblast differentiation in diabetic mice." (PMID 36632609, 2021). "This study is the first to demonstrate that individuals with severe isolated AS and concomitant type 2 diabetes, compared with no concomitant diabetes, exhibit enhanced valvular expression of NF-κB in association with increased expression of valvular FII, FXa and BMP-2." (PMID 34494136, 2021). "Although Bone morphogenetic protein-2 (BMP-2) is a known mediator of bone regeneration and vascular calcification, to date no study has investigated the relationship between BMP-2 and type 2 diabetes mellitus (T2DM) and its possible role in coronary artery disease (CAD)." (PMID 26003174, 2015). "However, the direct effect of BMP-2 on diabetes in vivo has not been reported thus far." (PMID 36909186, 2023). "Current and previous data may establish an interesting relation between VEGF and BMP2 especially in diabetes in which increased circulating BMP2, retinal BMP2 and VEGF elicit positive feedback in both endothelial and Müller cells to contribute to the retinal microvascular dysfunction in diabetes." (PMID 33584642, 2020).
osteosarcoma (41 papers, 2004 to 2024). A usually aggressive malignant bone-forming mesenchymal neoplasm, predominantly affecting adolescents and young adults. "A humanized bone-forming ectopic xenotransplantation model was set up by using hMSCs treated with BMP-2, and applied as pseudo-orthotopic approach to grow CI-competent (143B+/+) and CI-deficient (143B−/−) osteosarcoma cells in vivo." (PMID 31835761, 2019). "Promoted human osteosarcoma cell death, upregulated the BMP2/Smad signaling, promoted osteogenic differentiation, enhanced bone regeneration." (PMID 38791452, 2024). "CD109 is highly expressed in osteosarcoma, promote tumor cell migration via suppression of bone morphogenetic protein-2 (BMP-2)-induced Smad1/5/9 phosphorylation, where its expression correlates with poor prognosis." (PMID 39990858, 2024). "The multifunctional scaffolds promoted human osteosarcoma cell death and upregulated the BMP2/Smad signaling pathway to promote osteogenic differentiation in vitro in hBMSCs, under NIR irradiation." (PMID 38791452, 2024). "BMP2 acts as a potent tumor suppressor in gastric, renal cell, lung, and colorectal cancers, as well as osteosarcoma, inhibiting tumor growth by reducing the gene expression of oncogenic factors and inducing the differentiation of cancer stem cells." (PMID 38672212, 2024). "An earlier investigation documented the inhibitory prowess of BMP2 in curbing sarcomagenesis within “cancer stem cells” of osteosarcoma." (PMID 38049682, 2023). "BMP2 emerged as a driver of osteosarcoma cell migration, achieved through its modulation of fibronectin-integrin-β1 signaling pathways." (PMID 38049682, 2023). "In support of our data that 1,25D suppresses BMP signaling, 1,25D treatment of rat bone marrow stromal cells or UMR-106 rat osteosarcoma cells decreases Bmp2 mRNA expression." (PMID 37490334, 2023). "Osteosarcoma cells reportedly produce the osteogenic factor bone morphogenic protein 2 (BMP2) and form ectopic bone." (PMID 38062130, 2023). "SP7, the human homolog of the mouse Osterix gene, was expressed in human fetal osteoblasts and craniofacial osteoblasts, chondrocytes, and osteosarcoma cell lines that required BMP2 induction." (PMID 36408691, 2023). "BMP2 also enhanced osteosarcoma proliferation through Wnt/β‐catenin/epithelial‐mesenchymal transition (EMT) signaling pathway." (PMID 36408691, 2023). "Immortalized human osteoblastic cells (hFOB) or osteosarcoma cells (143b) were treated with 50 ng BMP2 for 5 days to induce osteogenic differentiation." (PMID 35635445, 2022). "BMP-2 was shown to promote migration of osteosarcoma cells in vitro possibly by promoting epithelial-mesenchymal transition." (PMID 35463995, 2021). "Hypoxia and interstitial acidosis are also important in the promotion of osteosarcoma bone metastasis, in part through activation of IL-8, IL-6, NF-κB1, colony-stimulating factors CSF2 and CSF3, BMP-2, CCL5, CXCL5 and CXCL1 in tumor-associated MSCs." (PMID 34831167, 2021). "Specifically, BMP-2 mediated β-catenin activation and the RhoC/Rho-associated kinase ROCK1/MAPK/Twist1 signaling pathway enhance osteosarcoma growth and promote EMT." (PMID 34831167, 2021). "Accordingly; fucoidan (U. pinnatifida) was able to stimulate osteoblast differentiation in MG-63 osteosarcoma cell line, by increasing the expression of BMP2 in vitro." (PMID 30621045, 2019). "That said, it is hoped that these results will drive future work intended to either demosntrate that BMP-2 is indeed cancer promoting or to demonstrate that BMP-2 can be safefly utilized within the context of osteosarcoma reconstructive surgery." (PMID 28264040, 2017). "A xenograft murine model (SaOS-LM7) was similarly used to assess osteosarcoma metastasis in vivo following triple-dose BMP-2 administration, given once per week." (PMID 28264040, 2017). "The effect of BMP-2 on in vitro tumor growth and development was assessed across multiple standard and patient-derived xenograft osteosarcoma cell lines." (PMID 28264040, 2017).
osteosarcoma (continued). "The purpose of this project was to evaluate the effect of exogenous BMP-2 on osteosarcoma migration and invasion across a panel of tumor cell lines in vitro and to characterize the effect of BMP-2 on pulmonary osteosarcoma metastasis within a xenograft model." (PMID 28264040, 2017). "Conversely, other investigators have characterized BMP-2 as an inhibitor of tumorgenesis in osteosarcoma." (PMID 28264040, 2017). "Coleusin factor, an inhibitor targeting BMP-2, exerted its anticancer effects on osteosarcoma by inducing osteoblast differentiation." (PMID 27661009, 2016). "Our findings present evidence on a potential therapeutic application of exogenous BMP-2 on human osteosarcoma by inducing differentiation of tumorigenic cells along an osteogenic pathway." (PMID 23900689, 2013). "Our study is the first to provide evidence indicating that exogenous BMP-2 induces bone formation in human osteosarcoma cells." (PMID 23900689, 2013). "Our previous studies demonstrated that BMP-2 inhibits the tumorigenicity of cancer stem cells identified as cells with high aldehyde dehydrogenase activity (ALDHbrcells) from the human osteosarcoma cell line OS99-1." (PMID 23900689, 2013). "To establish that the effect of E2 on BMP-2-induced transcription was indeed mediated via the ERα, we examined the effects of E2 on BMP-2-induced Smad6 mRNA in the human osteoblast-like osteosarcoma cell line U2OS stably expressing doxycycline-inducible ERα." (PMID 19821774, 2010). "Spindle cell tumor and osteosarcoma clones expressed high levels of BMPs, in particular BMP-2, -4 and -6." (PMID 19771160, 2009). "BMP-2 is thought to act as a potent inducer of tumor cell transdifferentiation in osteosarcoma." (PMID 35693928, 2022). "TGF-β/BMP2 signaling pathways also promoted osteosarcoma cell migration and invasion." (PMID 33436536, 2021). "In renal carcinoma and osteosarcoma, BMP2 inhibits cancer stemness." (PMID 34277708, 2021). "BMPs and BMP receptors are expressed in osteosarcoma, which has lead to the concern that administering exogenous BMP-2 may promote tumor recurrence." (PMID 28264040, 2017). "In large part, this is owing to the expression of BMPs and BMP receptors in osteosarcoma and the concern that exogenous BMP-2 may stimulate growth and proliferation of residual microscopic disease." (PMID 28264040, 2017). "Bone Morphogenetic Protein-2 (BMP-2) may offer the potential to enhance allograft-host osseous union in limb-salvage surgery following osteosarcoma resection." (PMID 28264040, 2017). "al. postulated in 1998 that BMP-2 decreases proliferation up to 35 % in human bone marrow cells representing early progenitors while other groups were unable to detect significant differences in osteosarcoma cell lines representing osteoblast-like-cells." (PMID 27206764, 2016). "They infected osteosarcoma cells with adenoviral vectors to secret BMP-2 and BMP-9." (PMID 23900689, 2013). "Our findings suggested that BMP-2 might induce human osteosarcoma cells to express an osteoblastic phenotype and thus activate osteogenic differentiation to form bone." (PMID 23900689, 2013). "BMP-2 induces bone formation in heterogeneous osteosarcoma cells and BMP-2 may have a promising therapeutic role for treating human osteosarcoma by inducing differentiation along an osteogenic pathway." (PMID 23900689, 2013). "Factors such as the concentration and distribution of these endogenous BMP compared to exogenous application of BMP-2 as done in this study may be the possible explanation for the proliferation of osteosarcoma cells observed in that investigation." (PMID 23900689, 2013). "Moreover, all of the clones, except CMT-U353B clone 6, expressed high levels of BMP-6 while BMP-2 expression varied among the osteosarcoma clones." (PMID 19771160, 2009).
osteosarcoma (continued). "Since Sp8 was found in human osteosarcoma cell lines and is important in skeletal development we examined the regulation of Sp8 by BMP-2 in the murine pluripotent embryonic cell line, C3H10T1/2 that can be induced to form a chondrogenic/osteoblastic phenotype by treatment with BMPs." (PMID 15533246, 2004). "In the present study, using regular RT-PCR, we determined that all 3 types of BMP receptors were expressed in freshly sorted ALDHbrand ALDHlocells derived from OS99-1 xenografts, suggesting that BMP-2 could bind to its receptors and activate cell signaling to affect osteosarcoma cell activities." (PMID 23900689, 2013). "This inquiry pinpointed osteosarcoma stem cells derived from the OS99-1 cell line, displaying elevated ALDH activity, a trait profoundly dampened by BMP2 treatment both in controlled laboratory conditions and in live subjects." (PMID 38049682, 2023). "Further research showed that Transmembrane protein 119 (TMEM119) promoted osteosarcoma cell proliferation, migration, and invasion via increasing the TGF‐β pathway‐related factors (BMP2, BMP7, and TGF‐β) expression." (PMID 36408691, 2023). "Bone morphogenetic protein-2 (BMP2) was shown to inhibit the proliferation and aggressiveness of osteosarcoma (OS) cells." (PMID 34377054, 2021). "Despite these findings, exogenous BMP-2 does not affect the metastatic phenotype of osteosarcoma cells." (PMID 35693928, 2022). "The aim of this study was to examine the effect of BMP-2 on the cell proliferation and osteogenic differentiation of human osteogenic progenitors of various origins: dental pulp stem cells (DPSC), human osteosarcoma cell line (Saos-2) and human embryonic palatal mesenchymal cell line (HEPM)." (PMID 29442285, 2018). "The addition of BMP-2 to osteosarcoma cell lines does not increase random cell migration or cell migration in response to a chemical stimulus in vitro, regardless of dose used." (PMID 28264040, 2017). "The addition of BMP-2 (0.5, 1, and 2 ug/ml) did not yield a decrease in the scratch wound width across all 8 osteosarcoma cell lines." (PMID 28264040, 2017). "Overall results from the in vivo and in vitro experiments in this study demonstrate that the addition of exogenous BMP-2 does not increase osteosarcoma proliferation, migration, invasion, or metastasis to the lungs." (PMID 28264040, 2017). "In the model systems tested, the addition of BMP-2 does not increase osteosarcoma proliferation, migration, invasion, or metastasis to the lungs." (PMID 28264040, 2017). "In this study, we likewise demonstrate that the systemic administration of exogenous BMP-2 does not increase metastasis in a xenograft model of osteosarcoma." (PMID 28264040, 2017). "The migration rate of osteosarcoma toward the chemoattractant did not increase with the addition of BMP-2 (0.5, 1, and 2 ug/ml)." (PMID 28264040, 2017). "Determining the bone formation of BMP-2 in osteosarcoma cellsin vivois essential for determining the potential use of BMP-2 clinically becausein vitroanalysis does not always reflect exactly thein vivosituation." (PMID 23900689, 2013). "When determining the efficacy of transduction in human mesenchymal stem cells and the Cal-72 human osteosarcoma cell line (data not shown), we observed an overwhelming (10- to 24-fold) increase of BMP-2 in cell culture supernatants in transfected cells compared to controls." (PMID 25924919, 2015). "Intriguingly, the exposure of osteosarcoma cells to diverse extracellular matrix (ECM) components, in the presence or absence of BMP2, led to an unexpected revelation." (PMID 38049682, 2023).